MAGI3 (membrane associated guanylate kinase, WW and PDZ domain containing 3)
Diseases named in the same sentence as MAGI3 in open-access papers (continued):
Sharing a sentence is not in itself a finding about the gene and the disease.
cervical cancer (1 paper, 2021). A primary or metastatic malignant neoplasm involving the cervix. "Furthermore, HPV18 rather than HPV16 is preferentially associated with downregulation of MAGI3 and activation of the Wnt/β‐catenin pathway in cervical cancer." (PMID 34510826, 2021). "In this study, we demonstrated that the PDZ protein membrane‐associated guanylate kinase, WW and PDZ domain containing 3 (MAGI3) inhibited the Wnt/β‐catenin pathway, and subsequently cervical cancer (CC) cell migration and invasion, via decreasing β‐catenin levels." (PMID 34510826, 2021). "By reducing the level of MAGI3 protein, HPV18 E6 promotes cervical cancer cell migration and invasion through activation of Wnt/β‐catenin signaling." (PMID 34510826, 2021).
chromophobe renal cell carcinoma (1 paper, 2025). Chromophobe renal cell carcinoma is a rare subtype of renal cell carcinoma, originating from the intercalating cells of the collecting ducts and macroscopically manifesting as a well-circumscribed, highly lobulated, solid tumor that is usually diagnosed at an early stage. "Based on the primary findings of this study, we have also preliminarily explored the potential of MAGI3 as a prognostic biomarker in other types of renal cancer, such as kidney renal papillary cell carcinoma and chromophobe renal cell carcinoma." (PMID 39956807, 2025).
Hypertension (1 paper, 2023). The presence of chronic increased pressure in the systemic arterial system. "Besides, miR-20b-5p contributed to the dysfunction of aortic smooth muscle cells by targeting MAGI3 in hypertension." (PMID 36846330, 2023).
hyperthyroidism (1 paper, 2014). Overactivity of the thyroid gland resulting in overproduction of thyroid hormone and increased metabolic rate. "The MAGI3 and BACH2 variants were associated with an increased risk of hyperthyroidism, and the MAGI3 variant was also associated with an increased risk of hypothyroidism." (PMID 24586183, 2014).
hypothyroidism (1 paper, 2014). Abnormally low levels of thyroid hormone. "MAGI3- rs1230666 was associated with an increased risk of overt hypothyroidism and increased TSH levels below the Bonferroni threshold (i.e., P = 0.05/5 = 0.01)." (PMID 24586183, 2014). "The MAGI3 variant was also associated with an increased risk of hypothyroidism (OR: 1.57, 95% CI 1.18–2.10, P = 1.9×10−3)." (PMID 24586183, 2014). "The MAGI3 SNP was associated with a substantially increased risk of hypothyroidism, and the BACH2 SNP showed a borderline significant association (P = 0.011) with a higher risk of increased TSH levels, which includes subjects with subclinical and overt hypothyroidism." (PMID 24586183, 2014).
metastatic disease (1 paper, 2020).
renal carcinoma (1 paper, 2025). A carcinoma arising from the epithelium of the renal parenchyma or the renal pelvis. "Firstly, we analyzed the expression changes of MAIG3 in Sunitinib resistant renal cancer cells in the GSE64052 database, and the results showed that the mRNA level of MAGI3 was significantly downregulated in Sunitinib-resistant cells." (PMID 39956807, 2025).
tumor (12 papers, 2015 to 2025). "Reduced MAGI3 expression showed a strong association with larger tumor size, revealing the link between MAGI3 and cell proliferation in ccRCC." (PMID 39956807, 2025). "Recently, aberrant m6A modification in the large internal exon of a tumour suppressor was shown to give rise to premature polyadenylation, leading to membrane associated guanylate kinase (MAGI3) inactivation." (PMID 30031372, 2018). "Given that the inhibition of the ERK signaling pathway is a major mechanism through which Sunitinib suppresses tumor cell proliferation, we examined the impact of MAGI3 expression on Sunitinib sensitivity in ccRCC cells." (PMID 39956807, 2025). "MAGI3 functions as a novel tumor suppressor in ccRCC, emphasizing the critical role of the MAGI3/MAS/ERK axis in Sunitinib resistance." (PMID 39956807, 2025). "Tumor cell proliferation is a major representative indicator of malignant phenotype, so the effects of MAGI3 expression on CRC cell proliferation was investigated." (PMID 35864508, 2022). "In summary, the present study has identified MAGI3 as a novel tumor suppressor in CRC and demonstrated its inhibition on proliferation by targeting c-Myc." (PMID 35864508, 2022). "Taken together, our results suggest that MAGI3 acts as a tumor suppressor by regulating proliferation and apoptosis in CRC cells." (PMID 35864508, 2022). "Experimentally, MAGI3 knockdown enhanced cell proliferation in vitro, while MAGI3 overexpression suppressed tumor growth in vivo." (PMID 34198584, 2021). "Apart from the four genes, other genes such as FBXL19, CSTF2, ZC3H11A, CRTC1 and MAGI3 influenced the formation and progression of human cancers with either carcinogenic or tumor-suppressive function." (PMID 30640723, 2019). "Our results underscore the importance of the MAGI3/YAP interaction in suppressing malignant transformation and implicate MAGI3 as a new potential component involved in the regulation of the Hippo tumor suppressor pathway." (PMID 27205883, 2016). "The YAP oncoprotein – a transcription co-activator that functions as a major effector of the Hippo tumor suppressor pathway – was identified to be top candidate interactor with MAGI3." (PMID 27205883, 2016). "In the Sunitinib-treated subcutaneous xenograft tumor model, MAGI3 overexpression led to significantly slowed tumor growth, reduced weight, and diminished levels of phosphorylated ERK and ki67, affirming the pivotal role of the MAS/MAGI3 axis in regulating Sunitinib sensitivity in ccRCC cells." (PMID 39956807, 2025). "Furthermore, in our modified model of AOM/DSS induced CRC, MAGI3−/− mice showed higher disease activity index and a significant higher tumor number and load compared to their wild-type controls." (PMID 35864508, 2022). "Furthermore, one study found that MAGI3 with high levels of m6A methylation led to premature of polyadenylation, leading to this tumor suppressor gene to switch its function to promote tumor progression and ultimately facilitating the tumorigenesis of BC." (PMID 34381710, 2021). "Thus, for intron retention, the expected distribution of reads upstream and downstream of the cryptic PAS in MAGI3 intron 10 can be compared to the empirical read distributions in the 29 samples with tracts of overlapping intronic reads (26 tumor, 3 normal)." (PMID 27205883, 2016). "However, a specific role for MAGI3 as a tumor suppressor in human cancer has remained elusive, due to the apparent infrequent alteration of the gene in cancer and the lack of cancer-relevant mechanistic evidence." (PMID 27205883, 2016). "MAGI3 expression was negatively correlated with tumor grade and poor prognosis." (PMID 26452219, 2015). "MAGI3 have been reported binding with PTEN and β-catenin to regulate PI3K/AKT and Wnt signaling respectively, to inhibit tumor formation and progression." (PMID 35864508, 2022).
tumor (continued). "By defining the protein-protein interaction network of MAGI3, we have uncovered the previously unknown interaction between MAGI3 and YAP, an oncoprotein that represents the major downstream effector of the Hippo tumor suppressor pathway." (PMID 27205883, 2016).
cancer (10 papers, 2013 to 2025). A tumor composed of atypical neoplastic, often pleomorphic cells that invade other tissues. "Mutations in other cancer‐associated genes such as MAGI3, TSC1, PTPN4, RAB3IP, and RYR1 were also identified." (PMID 26432421, 2015). "By identifying m6A as a cis-acting epitranscriptomic mark associated with MAGI3 mRNA shortening, we have drawn an unexpected connection between large internal exon m6A modifications in MAGI3 and the expression of cancer-associated, pPA-truncated MAGI3 transcripts." (PMID 29362392, 2018). "The loss of MAGI3 expression in ccRCC patients activated the ERK signaling pathway, contributing to both cancer progression and Sunitinib resistance." (PMID 39956807, 2025). "Loss of MAGI3 expression in ccRCC patients activated the ERK signaling pathway, contributing to both cancer progression and Sunitinib resistance." (PMID 39956807, 2025). "In this study, MAGI3 is found to promote c-Myc protein ubiquitin–proteasome degradation, subsequently attenuates c-Myc activation in a broad range of cancers besides CRC." (PMID 35864508, 2022). "How cancer cells modulate m6A levels in the MAGI3 large internal exon to trigger pPA, and how this modulation of levels impacts pPA of MAGI3 from a mechanistic standpoint, are new questions that require further investigation." (PMID 29362392, 2018). "Collectively, these data indicate that MAGI3 alterations in cancer may occur much more frequently than previously appreciated and support the clinical relevance of MAGI3 truncations as driver alterations." (PMID 27205883, 2016). "In the past, a number of observations have supported the possibility that MAGI3 may be involved in cancer." (PMID 27205883, 2016). "In human cancer, MAGI3 is not frequently altered by nonsynonymous mutations or copy number losses, and has not been previously nominated as a driver." (PMID 27205883, 2016). "Thus, we hypothesized that a molecular mechanism which normally limits the usage of the intronic PAS downstream of the large internal exon of MAGI3 may be deregulated in cancer." (PMID 29362392, 2018). "Determining whether pPA events in cancer occur in other genes beside MAGI3, and whether pPA is triggered widely throughout the transcriptome or focally restricted to susceptible intronic PAS, are important future directions but beyond the scope of the current study." (PMID 27205883, 2016). "Knockdown of MAGI3 increases expression of NHERF-2, which enhances cell growth, COX-2 expression and ensures cancer resistance to chemotherapy." (PMID 23844591, 2013). "It is well known that a high level of c-Myc is closely correlated with chemotherapy resistance in many cancers, including CRC cell, reminding that dysregulated low level of MAGI3 in CRC may reduce chemosensitivity through accumulation of c-Myc." (PMID 35864508, 2022). "MIPEP expression was also significantly increased (p < 0.05) in grade II tumors comparing to the grade I. We also showed significantly (p < 0.05) and highly significant (p < 0.001) decreased expression of MAGI3 and ZFP37 (respectively) in the most malignant tumors." (PMID 23844591, 2013). "In the human mammary MDA-MB-231 cancer cells, the premature polyadenylation of MAGI3 produces a truncated protein depleted of PDZ2-PDZ5 (MAGI3pPA) that acts in a dominant-negative manner to prevent full-length MAGI3 from interacting and impairing YAP1 nuclear translocation." (PMID 34503076, 2021).
infection (1 paper, 2021). The state of being infected such as from the introduction of a foreign agent such as serum, vaccine, antigenic substance or organism. "In this study, we demonstrated that infection with HPV18 was associated with a significantly lower level of MAGI3 than paracancerous tissues; MAGI3 inhibited CC cell migration and invasion via attenuation of β‐catenin protein level and Wnt signaling." (PMID 34510826, 2021).
MAGI3 also shares sentences with these, for which no sentence is quoted: inflammatory bowel disease (2 papers); prostate carcinoma (2); Type 1 diabetes (2); ulcerative colitis (2); autoimmune disease (1); autoimmune thyroid disease (1); basal cell carcinoma (1); brain tumor (1); celiac disease (1); colon adenocarcinoma (1); colorectal tumor (1); glioblastoma (1); Hashimoto thyroiditis (1); hepatocellular carcinoma (1); liver cancer (1); lung carcinoma (1); pancreatic cancer (1); renal cell carcinoma (1); rheumatoid arthritis (1); thyroid disease (1); triple-negative breast carcinoma (1).